PROX1 (prospero homeobox 1)
Diseases named in the same sentence as PROX1 in open-access papers (continued):
Sharing a sentence is not in itself a finding about the gene and the disease.
tumor (continued). "Matching our RNA-Seq results, PROX1 expression was increased in populations of cells in an AR activity–low tumor and was highly expressed in DNPC and NEPC tumors but not in ARPC." (PMID 40454483, 2025). "Using the Pearson’s Chi-square test, there were no statistically significant variations in PROX1 expression concerning the factors; patient age (P = 0.157), gender (P = 0.373), tumor site (P = 0.801), and incidence of mortality (P = 0.078)." (PMID 40660330, 2025). "PROX1 and MTA1 have the potential to be utilized as predictors of progression and recurrence in SGCs because they are good indicators of LVI, recurrence, distant metastasis, and tumor stage." (PMID 40660330, 2025). "PROX1 expression, on the other hand, differed significantly by tumor size (P = 0.000), incidence of nodal (P = 0.007) and distant metastasis (P = 0.001), TNM clinical stage (P = 0.000), and incidence of tumor recurrence (P = 0.001)." (PMID 40660330, 2025). "PROX1 was also highly expressed in a separate NEPC tumor cell population that was AR and KLK3 negative but positive for NEPC markers, including INSM1." (PMID 40454483, 2025). "Here Prox1 OE also reduced the number of tumor nodules (3.25 versus 19.5 nodules), all lacking Prox1-IRES-GFP, and extended survival from 26.5 to 47.5 days." (PMID 39948437, 2025). "PROX1 positivity was detected in the nuclear part of tumor cells, while it was absent in surrounding stromal and inflammatory cells." (PMID 40843762, 2025). "Notably, immunohistochemical analysis showed that both PROX1 and the cholesterol synthesis enzyme DHCR7 were highly expressed in the tumor tissue compared to the adjacent healthy muscle." (PMID 41249736, 2025). "The PROX1 transcription factor is responsible for the expression of the vascular endothelial growth factor receptor 3 (VEGFR3), which is stimulated by tumour-cell-derived VEGFC; this triggers tumour lymphangiogenesis and establishes the main route of dissemination for solid tumours." (PMID 38203852, 2024). "In addition, western blot analyses revealed that PROX1 and SCD proteins were upregulated in the tumor lysates compared to those in their normal counterparts." (PMID 36815375, 2023). "This revealed that 25% of tumor cells were CD34+/Prox-1+, 26% CD34+ only, and 4% Prox-1+ only." (PMID 37046832, 2023). "Consistently, c-Myc over-expression from an artificial promoter that was not targeted by Prox1 reversed Prox1’s anti-tumor effects." (PMID 37508533, 2023). "Moreover, PROX1 promotes metabolic adaptation and expansion of the CRC stem cell population to fuel tumor growth and metastases, highlighting the critical role of PROX1 in CRC tumorigenesis." (PMID 36815375, 2023). "However, in the current study, we found that 25% of the KS tumor cells were co-expressing CD34 and Prox-1 which implies two scenarios that cannot, at this time, be distinguished." (PMID 37046832, 2023). "We meta-analyzed 728 patients from four studies and discovered that PROX1 expression in GC patients is not related to tumor size (≥ 5 cm and < 5 cm) (OR: 0.889, 95% CI 0.502–1.576, P = 0.687)." (PMID 35346069, 2022). "Thus, AMPK-mediated PROX1 phosphorylation dictates BCAA metabolism and mTOR signalling to limit glucose consumption, possibly facilitating tumour cell adaptation to metabolic stresses." (PMID 36433955, 2022). "It is also reported that overexpression of PROX1 increased lymphatic endothelial cell invasion and tube formation by increasing VEGF-C and VEGF-D expression which may result tumor lymphangiogenesis." (PMID 35346069, 2022). "According to the staining results for PROX1 expression, lymphatics were visible only in the tumor capsule and in the surrounding liver but were not visible within the tumor or between the nodules, in either HCC or in liver metastases." (PMID 35885529, 2022). "Moreover, the patients with LN metastasis or advanced tumor stage had higher serum EV-packaged hnRNPA1, SAE1, and PROX1 expression levels." (PMID 35579947, 2022).
tumor (continued). "Viral G-protein coupled receptor (vGPCR) could upregulate PROX1 during LEC reprogramming and render cells enhanced cell proliferation, migration, and tumor formation." (PMID 34492084, 2021). "Prox1 is a transcription factor involved in tumor progression, and it is not expressed in normal ISCs." (PMID 34414192, 2021). "Finally, we examined the association between HIF‐1α and the key factor in lymphangiogenesis, Prox1, and showed that HIF‐1α+ tumor cells simultaneously expressed Prox1." (PMID 31960509, 2020). "miR-9 is regulated by prospero homeobox 1 (PROX1), a tumor suppressor." (PMID 26662959, 2016). "In contrast to PROX1, expression of LYVE1, one of the most widely used markers of LECs in normal and tumor tissues, was restricted to the paracortical and medullary sinuses in most LNs, and was not expressed by PROX1+ LECs in the subcapsular and trabecular sinuses." (PMID 24733110, 2014). "Prox1 alone is not able to trigger tumor genesis, but it is able to drive tumor progression via disruption of cell polarity and adhesion." (PMID 23675176, 2010). "Confocal imaging revealed that 3% of Podoplanin+ tumor lymphatic endothelial cells (TLEC) as well as 3.5% of Prox-1+ or LYVE-1+ TLEC co-expressed GFP, indicating that approximately 3% of tumor-surrounding lymphatic endothelial cells are derived from the bone marrow." (PMID 19759906, 2009). "Importantly, the tumor-suppressive effect of SMARCA4 knockdown could be rescued by histone deacetylase inhibitors (HDACi), achieving a level of recovery comparable to PROX1 overexpression." (PMID 41881959, 2026). "Additionally, concerning the clinical factors there were significant statistical differences in PROX1 expression based on the following variables: TNM clinical stage, tumor size, nodal and distant metastasis incidence, and tumor recurrence incidence (P < 0.05)." (PMID 40660330, 2025). "Furthermore, we did not identify cells expressing PROX1 at baseline in a patient whose progression tumor biopsy after AR inhibition was most consistent with DNPC." (PMID 40454483, 2025). "The expression level of LYVE–1 in tumor tissues of patients with lymph node involvement was similar with that in patients without lymph node involvement (P = 0.354), and the similar results were found for VEGFR–3 (P = 0.631), Podoplanin (P = 0.490), and Prox–1 (P = 0.503)." (PMID 29162097, 2017). "In the present study, none of the grade 1 tumours had high PROX1 expression." (PMID 21970873, 2011). "The reason for the lack of PROX1 expression in highly differentiated tumours remains unknown, but this could be due to the lower Wnt pathway activation." (PMID 21970873, 2011). "Our results indicated that over expression of Prox1 increases AKT phosphorylation and PI3 kinase expression, thereby increasing transfected CHO cells proliferation via activation of AKT signaling pathway; thus, it opens a new avenue to intervene in tumor progression and metastasis in the future." (PMID 23675176, 2010). "A total of 225 high-quality cells from control and 356 from tumor-draining LNs were included in the downstream analysis and their LEC identity could be confirmed by the expressions of endothelial cell markers Cd31 (Pecam1) and VE-cadherin (Cdh5) as well as lymphatic markers Prox1 and Vegfr3 (Flt4)." (PMID 35892863, 2022). "Previous reports have shown CD11b+ myeloid cells express LYVE-1 and Prox-1 only when attached to the tumor vasculature but not unattached, indicating that vascular-immune interactions might play a prominent role in the expression of these proteins in the immune cells." (PMID 24124909, 2013). "In cases of invasive squamous cell carcinoma of the uterine cervix, LVD, as assessed by the lymphatic markers D2-40, LYVE-1, and PROX1, did not correlate with LN metastasis, FIGO stage, or tumor grade." (PMID 35885529, 2022).
tumor (continued). "We then assessed the expression of Prox1 and FOXC2 mRNA in 5 samples of non-tumor oral mucosa, 10 samples of metastasis-negative OSCCs, and 5 samples of metastasis-positive OSCCs." (PMID 24647631, 2014). "Although PROX1 is not currently a therapeutic target, its involvement in VEGF-C/VEGFR-3 signaling and lymphatic dissemination suggests its potential role in modifying the tumor microenvironment." (PMID 40843762, 2025). "Compared with tumor cells at the primary site, metastatic tumor cells still retained high expressions of KRT8 and KRT18, whereas metastatic tumor cells no longer expressed MMRN1, PROX1, TCF7L1, SCG3 and SV2C." (PMID 35494058, 2022). "According to this study, while lineage-labeled cells integrated within tumor-related lymphatic vessels following subcutaneous implantation of either LLC or EL4 lymphoma cells, they did not express PROX1, thus arguing against a possible mechanism of differentiation of macrophages to LECs." (PMID 33071831, 2020). "Stainings of LN sections for LYVE-1, Prox1, and the proliferation marker Ki67 confirmed that the LEC proliferation rate was increased both in the subcapsular sinus and the medullary sinus of 4T1 tumor-draining, but not non-draining, LNs." (PMID 30590031, 2018). "Although PROX1 does not appear to be a specific RCC marker, its significance in predicting tumor progression and prognosis suggest that it could benefit RCC patients." (PMID 24797520, 2014). "Medullary sinuses without tumor cells expressed MARCO, but those containing tumor cells in the same LNs lost MARCO expression, despite maintaining expression of the lymphatic identity marker PROX1, indicating that tumor metastasis through the sinuses alters LEC phenotypes." (PMID 41249124, 2025). "Importantly, the pre–AR inhibitor treatment ARPC tumor (2623-1) and post–AR inhibitor treatment DNPC tumor (2623-2) were taken from the same patient, demonstrating that preexisting PROX1-high cells were not present in the pretreatment ARPC tumor we examined." (PMID 40454483, 2025). "However, we could not find any significant differences between Prox1 expression levels between Apc1638N/+ and Apc1638N/+/KRASV12G tumour cells both in the original microarray data and upon qPCR validation." (PMID 24069241, 2013).
cancer (80 papers, 2008 to 2025). A tumor composed of atypical neoplastic, often pleomorphic cells that invade other tissues. "Conversely, in hepatocellular and pancreatic malignancies, PROX1 expression has been linked to more favorable differentiation states and prolonged patient survival." (PMID 40843762, 2025). "The heterogeneity of PROX1 associations across various subgroups underscores its pleiotropic role in cancer biology." (PMID 40843762, 2025). "In some contexts, PROX1 expression in cancer cells has been associated with increased invasiveness and lymphatic metastasis." (PMID 39328205, 2024). "Since PROX1 was first linked to cancer through its ability to regulate cell differentiation 30, evidence for the importance of aberrant PROX1 expression in human malignancy has accumulated." (PMID 36594098, 2023). "Here, clinical data, in vitro cell lines and in vivo xenograft mouse models were utilized in an in-depth exploration of the contribution of PROX1 to cancer cell metabolism and the underlying mechanism." (PMID 36594098, 2023). "Subsequently, the E#4 was defined as lymphatic endothelial (LEC) cells by the marker genes (LEC) (e.g., PDPN and PROX1), and E#1 was defined as carcinoma‐associated fibroblasts derived endothelial cells (CAFsEc) (e.g., S100A4)." (PMID 37726969, 2023). "Collectively, our results demonstrate that deficiency of the LKB1-AMPK axis in cancers reactivates PROX1 to sustain intracellular BCAA pools, resulting in enhanced mTOR signalling, and facilitating tumourigenesis and aggressiveness." (PMID 36433955, 2022). "Several researchers have conducted in vitro and animal studies to elucidate the molecular pathways and mechanisms underlying PROX1 multifactorial activity in cancer." (PMID 35885529, 2022). "Collectively, the deficiency of the LKB1-AMPK axis in cancers reactivates PROX1 to sustain intracellular BCAA pools and mTOR signalling, facilitating tumourigenesis and aggressiveness." (PMID 36433955, 2022). "Research on cancer metastasis have implicated the potential roles of Prox1 in the regulation VEGF-C autocrine signaling." (PMID 33263009, 2020). "Herein, we focused on prospero homeobox 1 (PROX1), which we found to be strongly linked to the emergence of lineage plasticity early on and which we determined to be critical for promoting important cancer hallmarks in tumors undergoing lineage transitions." (PMID 40454483, 2025). "Furthermore, Prox1 has been implicated in a large number of human cancers, including blood, pancreatic, liver, colon, lung, and nervous system-related tumors, displaying both suppressing and oncogenic roles in a tissue dependent manner." (PMID 37508533, 2023). "There is evidence that PROX1 may be associated with both the progression and even the suppression of tumorigenesis, but this is highly dependent upon the specific type of cancer." (PMID 35885529, 2022). "In addition, the phosphorylation of PROX1, which impairs its oncogenic function, is markedly reduced in cancers, and lower Ser79 phosphorylation levels are associated with unfavourable patient survival." (PMID 36433955, 2022). "To better understand the relation of pulmonary lymphatics to lung metastases in 3D, we also imaged fixed, cleared lungs of Prox1-eGFP mice 18 days after seeding with B16.F10-mCherry cancer cells." (PMID 39969509, 2025). "On the other hand, PROX1 RNA interference experiments in DNPC and NEPC established a key role of PROX1 in regulation of important cancer hallmarks that sustain lineage plasticity cells." (PMID 40454483, 2025). "This study identifies candidate safeguard repressor transcription factors that repress alternate lineages in mature cell types and provides functional evidence that Prox1 performs such a function in hepatocytes during reprogramming, regeneration and in cancer." (PMID 39948437, 2025).
cancer (continued). "Cases of advanced clinical stages (III and IV) had carcinomas presented mainly positive PROX1 expression (26 cases, 81.3%)." (PMID 40660330, 2025). "There were significant statistical differences found between the expression of PROX1 and the histological type and grade of carcinoma as well as the incidence of lymph vascular invasion (P < 0.000)." (PMID 40660330, 2025). "The overexpression of miR-9 can lead to EMT, which is regulated by c-Myc and Prospero homeobox 1 (PROX1), contributing to cancer cell metastasis." (PMID 38801504, 2024). "Studies have suggested that PROX1 expression in cancer cells can modulate their invasive potential and metastatic propensity." (PMID 39328205, 2024). "First, the expression of the PROX1 pathway downstream target genes and CAF markers were examined, and the results demonstrated that PROX1 promoted cancer progression, following the results of the migration and invasion assays." (PMID 38244581, 2024). "Though the regulatory influence of PROX1 on cancer progression and chemoresistance is increasingly recognized, the fundamental mechanisms are yet to be clarified." (PMID 38244581, 2024). "The correlation between PROX1 expression and cancer progression has been explored in several cancer types." (PMID 37847340, 2024). "We found that PROX1 regulates glycolysis and mitochondrial respiration, which are fundamental for sustaining cancer cell proliferation." (PMID 36594098, 2023). "To achieve this, we co-expressed c-Myc and Prox1 in MCF7 cancer cells and compared them to cells over-expressing only Prox1 or GFP." (PMID 37508533, 2023). "Therefore, a better understanding of the molecular mechanisms regulating PROX1 expression not only expands our knowledge of normal lymphatic development and function, but also provides novel insights into the pathophysiology of lymphatic-associated diseases and cancer." (PMID 37407839, 2023). "Further studies should examine the effects of small molecules that target PROX1 on cancer cell metabolism and SIRT3 expression." (PMID 36594098, 2023). "PROX1 is a gene that plays a critical role in embryonic development and is involved in the progression of various cancers." (PMID 37685269, 2023). "Nevertheless, we believe that our findings highlight the ability of PROX1 to promote carcinogenesis by recruiting transcriptional coregulators to promote cancer cell proliferation and the expression of genes controlling glucose metabolism." (PMID 36594098, 2023). "Our observations suggest that Prox1 is a key transcription regulator for the prevention of cancer-specific metabolic reprogramming." (PMID 37508533, 2023). "In this regard, we over-expressed GFP or Prox1 in MDA-MB-231 cancer cells (adenoviral system) and then transplanted them subcutaneously into NOD/SCID mice." (PMID 37508533, 2023). "Second, the discovery and characterization of several biomarkers including VEGF-C, LYVE-1, Podoplanin and Prox-1 have opened new vistas in the understanding of the induction of lymphangiogenesis by cancer cells." (PMID 34767139, 2022). "PROX1 has been used as a lymph-specific marker during the histological examination of cancer tissues and has been also studied at the molecular level to investigate its role in tumorigenesis." (PMID 35885529, 2022). "Previous studies have explored the relationship between PROX1 expression and clinicopathological parameters and prognosis in various cancers." (PMID 35346069, 2022). "The results showed that PROX1 expression was higher in cancer tissues compared with the matched adjacent normal tissues." (PMID 35342346, 2022). "At the same time, studies have found that the alteration of PROX1 are related to the malignant biological behavior of different cancers, and also involved in the occurrence and progression of cancer." (PMID 35342346, 2022). "The aim of the present study is to present and summarize existing data concerning PROX1 expression in various cancer types, exploring its role in tumorigenesis." (PMID 35885529, 2022).